IGSF5 (immunoglobulin superfamily member 5)
Description:
Provides, together with MAGI1, an adhesion machinery at tight junctions, which may regulate the permeability of kidney glomerulus and small intestinal epithelial cells. Mediates calcium-independent homophilic cell adhesion. In testis, it may function as a cell adhesion molecule rather than a tight-junction protein. It may participate in the adhesion between spermatogonia-spermatogonia, spermatogonia-Sertoli cells, and Sertoli cells-Sertoli cells (By similarity).
Synonyms: JAM4; GSF5
Tractability: Antibody: UniProt places it where antibodies can reach, with medium confidence; UniProt predicts a signal peptide or a membrane-spanning region; its Gene Ontology location is reachable by antibodies, with medium confidence.
Gene: Protein-coding gene on chromosome 21 (39,745,183 to 39,802,081, forward strand). Ensembl gene ENSG00000183067.
Subcellular location: Apical cell membrane; Cell junction, tight junction
Subcellular location (Human Protein Atlas): Focal adhesion sites
Gene Ontology:
Molecular function: protein binding
Biological process: cell-cell adhesion
Cellular component: apical plasma membrane; bicellular tight junction; cell surface
Genetic constraint (gnomAD): Loss-of-function variants: 30 observed, 27.74 expected, observed/expected ratio (o/e) 1.08, 90% interval 0.81 to 1.47. The upper end of that interval is the gene's LOEUF score, 1.47, which puts it in group 6 of 6, group 1 being the genes least tolerant of losing a copy. Missense variants: 406 observed, 445.89 expected, observed/expected ratio (o/e) 0.91, 90% interval 0.84 to 0.99. Synonymous variants: 148 observed, 159.51 expected, observed/expected ratio (o/e) 0.93, 90% interval 0.81 to 1.06.
Homologues: Orthologues: chimpanzee IGSF5 (96% identical), macaque IGSF5 (82% identical), tropical clawed frog igsf5 (23% identical), zebrafish ntm (14% identical), Caenorhabditis elegans rig-5 (13% identical), Drosophila melanogaster klg (13% identical), Drosophila melanogaster DIP-kappa (12% identical), Drosophila melanogaster DIP-zeta (12% identical), Drosophila melanogaster Ama (11% identical), Drosophila melanogaster DIP-iota (11% identical), Drosophila melanogaster Lac (11% identical), Drosophila melanogaster DIP-eta (11% identical), and 5 more. Paralogues in human: NEGR1 (14% identical), NTM (14% identical), OPCML (14% identical), IGLON5 (13% identical), LSAMP (12% identical).
Diseases named in the same sentence as IGSF5 in open-access papers:
IGSF5 is named in the same sentence as 5 diseases in open-access papers, as found by Europe PMC text mining. Sharing a sentence is not in itself a finding about the gene and the disease. The quoted sentences say what the papers report.
asthma (1 paper, 2022). "In contrast to the associations of IKZF4 and IGSF5 seen in obese asthma, the genetic association of SLC9A4, encoded by the solute carrier family 9 member A4 gene, is only seen in non-obese asthma." (PMID 35524249, 2022). "Regarding its association with asthma, coding variants of IGSF5 have been shown of correlation with inflammatory cell infiltration due to impaired adhesion function, and IGSF5 has been reported in the GWAS of coronary heart disease in the African American population." (PMID 35524249, 2022). "Five genes previously reported in a genome-wide association study (GWAS) on asthma, including TSLP, SLC9A4, PSMB8, IGSF5, and IKZF4 were demonstrated association in the asthma vs. control analysis." (PMID 35524249, 2022). "The associations of IKZF4 and IGSF5 are only associated with obese asthma; and the association of SLC9A4 is only observed in non-obese asthma." (PMID 35524249, 2022). "Three of the genes delineated clear heterogeneous effects between obese asthma and non-obese asthma, with IKZF4 and IGSF5 showing association with obese asthma, and SLC9A4 with non-obese asthma." (PMID 35524249, 2022).
influenza (1 paper, 2024). An acute viral infection of the respiratory tract, occurring in isolated cases, in epidemics, or in pandemics; it is caused by serologically different strains of viruses (influenzaviruses) designated A, B, and C, has a 3-day incubation period, and usually lasts for 3 to 10 days. "Of the four likely effector genes of the influenza loci, ST6GAL1 and B3GALT5 are strong biological candidates (ADIPOQ and IGSF5 are discussed in the Supplementary Note)." (PMID 39103650, 2024).
IGSF5 also shares sentences with these, for which no sentence is quoted: coronary heart disease (1 paper); Obesity (1); tumor (1).